BAK1 (BCL2 antagonist/killer 1)
Description:
Plays a role in the mitochondrial apoptotic process. Upon arrival of cell death signals, promotes mitochondrial outer membrane (MOM) permeabilization by oligomerizing to form pores within the MOM. This releases apoptogenic factors into the cytosol, including cytochrome c, promoting the activation of caspase 9 which in turn processes and activates the effector caspases.
Synonyms: BAK; BCL2L7; CDN1; BAK-LIKE
Tractability: Small molecule: a structure with a bound ligand is known; a high-quality ligand is known. Antibody: UniProt predicts a signal peptide or a membrane-spanning region. PROTAC: its protein half-life has been measured; a small molecule that binds it is known.
Gene: Protein-coding gene on chromosome 6 (33,572,547 to 33,580,305, reverse strand). Ensembl gene ENSG00000030110.
Subcellular location: Mitochondrion outer membrane
Pathways (Reactome):
Programmed Cell Death: Activation and oligomerization of BAK protein; Pyroptosis; Release of apoptotic factors from the mitochondria
Gene Ontology:
Molecular function: identical protein binding; porin activity; protein binding; protein heterodimerization activity; protein homodimerization activity; transmembrane transporter binding; channel activity; BH domain binding; heat shock protein binding; protein-containing complex binding; protein-folding chaperone binding
Biological process: apoptotic process; apoptotic signaling pathway; cellular response to mechanical stimulus; cellular response to UV; establishment or maintenance of transmembrane electrochemical gradient; intrinsic apoptotic signaling pathway; negative regulation of mitochondrial outer membrane permeabilization involved in apoptotic signaling pathway; negative regulation of release of cytochrome c from mitochondria; positive regulation of apoptotic process; positive regulation of protein-containing complex assembly; positive regulation of proteolysis; regulation of mitochondrial membrane permeability; regulation of mitochondrial membrane potential; release of cytochrome c from mitochondria; cellular response to unfolded protein; endoplasmic reticulum calcium ion homeostasis; extrinsic apoptotic signaling pathway in absence of ligand; intrinsic apoptotic signaling pathway in response to DNA damage; intrinsic apoptotic signaling pathway in response to endoplasmic reticulum stress; negative regulation of apoptotic process; positive regulation of IRE1-mediated unfolded protein response; positive regulation of mitochondrial outer membrane permeabilization involved in apoptotic signaling pathway; positive regulation of release of cytochrome c from mitochondria; animal organ regeneration; endocrine pancreas development; and 11 more
Cellular component: BAK complex; Bcl-2 family protein complex; mitochondrial outer membrane; mitochondrion; pore complex; cytoplasm; cytosol; endoplasmic reticulum; mitochondrial membrane
Genetic constraint (gnomAD): Loss-of-function variants: 19 observed, 23.3 expected, observed/expected ratio (o/e) 0.82, 90% interval 0.57 to 1.2. The upper end of that interval is the gene's LOEUF score, 1.2, which puts it in group 5 of 6, group 1 being the genes least tolerant of losing a copy. Missense variants: 194 observed, 280.1 expected, observed/expected ratio (o/e) 0.69, 90% interval 0.62 to 0.78. Synonymous variants: 86 observed, 110.36 expected, observed/expected ratio (o/e) 0.78, 90% interval 0.65 to 0.93.
Homologues: Orthologues: chimpanzee BAK1 (99% identical), macaque BAK1 (96% identical), dog BAK1 (89% identical), pig BAK1 (83% identical), rabbit BAK1 (79% identical), mouse Bak1 (77% identical), rat Bak1 (76% identical), guinea pig BAK1 (60% identical), tropical clawed frog BAK1 (41% identical), Caenorhabditis elegans ced-9 (16% identical). Paralogues in human: BCL2 (24% identical), BCL2L1 (22% identical), BCL2L2 (22% identical), MCL1 (21% identical), BAX (19% identical), BOK (19% identical), BCL2A1 (17% identical), BCL2L10 (14% identical).
Diseases named in the same sentence as BAK1 in open-access papers:
BAK1 is named in the same sentence as 115 diseases in open-access papers, as found by Europe PMC text mining. Sharing a sentence is not in itself a finding about the gene and the disease. The quoted sentences say what the papers report.
breast cancer (34 papers, 2011 to 2025). A primary or metastatic malignant neoplasm involving the breast. "Overexpression of BAK1 has previously been associated with a favourable prognosis in breast cancer, while BOK, BAK1 and HRK as effectors are inserted into the mitochondrial outer membrane, resulting in MOMP without sequestration by the guardians." (PMID 32419250, 2020). "Similar to miR-21, miR-125b drives chemoresistance in breast cancer and non-small cell lung cancer by targeting the mRNA encoding the apoptotic protein BCL2 antagonist killer 1 (BAK1)." (PMID 33322770, 2020). "In particular, the treatment with calcitriol and tacalcitol has been shown to cause a decrease in miR‐125b as well as an increase in pro‐apoptotic protein BAK1 in MCF‐7 breast cancer cells." (PMID 33332677, 2021). "The drug was also able to significantly increase the nuclear condensation, and modulated the expression of certain genes involved in breast cancer, such as caspases 3, and 9, BAK-1, C-MYC, BCL2L1, BCL-10, and BCL-2." (PMID 32746451, 2020). "In the luminal breast cancer cell line, we demonstrated that the reactivation of this miRNA affects the expression and protein levels of BAK1, a target involved in anti-apoptosis." (PMID 27386402, 2016). "Conversely, in its “devil” role, high miR-125b expression levels confer to breast cancer cells resistance to paclitaxel by targeting BAK1 and are detected in miRNA signatures present in Tam- or fulvestrant-resistant breast cancer cell lines." (PMID 25633049, 2015). "The high-level expression of miR-125 endue the tolerance of breast cancer cells to docetaxel by suppressing the expression of Bak1." (PMID 25342041, 2014). "For example, miR-125b has been shown to directly target BAK1 and downregulate its expression in prostate cancer cells and breast cancer cells." (PMID 23322811, 2013). "Similarly, miR-125b directly targets BAK1 and contributes to breast cancer progression, while BAK1 repression mediated by specific miRNAs has been demonstrated to promote the growth of prostate cancer cells." (PMID 40951345, 2025). "In multiple bioinformatics studies, BAK1 has served as part of prognostic models, demonstrating critical predictive roles in common malignancies such as esophageal squamous cell carcinoma, lung adenocarcinoma, hepatocellular carcinoma, and breast cancer." (PMID 40951345, 2025). "For paclitaxel resistance, the following miRNAs are relevant, miR-17-5P for the target PTEN in ovarian cancer, miR-30c for the targets VIM, IL-11 in breast cancer, miR-125b for Sema4C and Bak1 in breast cancer, and miR-100 for mTOR, miR-145 for P-gp in ovarian cancer, and miR-181a for PTEN in NSCLC." (PMID 35582143, 2019). "Also miR-125b that targets BAK1 and which is highly expressed in prostate cancer and in breast cancer cells, contributes to disease progression and chemoresistance." (PMID 26694467, 2015). "Bak1 is also a direct target of miR-125b, and restoring Bak1 expression in breast cancer cells could recover paclitaxel sensitivity, overcoming miR-125b-mediated paclitaxel resistance." (PMID 24106980, 2013). "One recent study showed that pro-apoptotic Bcl-2 antagonist killer 1 (Bak1) was a direct target of miR-125b, and suppression of Bak1 gene expression through overexpression of miR-125b inhibited Taxol-induced apoptosis and led to an increased resistance to Taxol in breast cancer cells." (PMID 22523546, 2012). "At least three genes from this list were involved in the formation of carcinomas, including breast carcinoma (CASP8, HSPA4, BCL2L11), prostate carcinoma (BCL2, CASP8, BCL2L11, ATM), and chronic lymphocytic leukemia (BCL2, CASP8, FAS, BCL2L11, BAK1)." (PMID 37298337, 2023). "Studies have shown that KDM5A promotes the resistance of breast cancer cells to clinical drugs such as trastuzumab and erlotinib by blocking the regulation of p21 and BCL2-antagonist/killer 1 (Bak1)." (PMID 35493099, 2022).
breast cancer (continued). "The expression of miR-125b is downregulated in various human cancers including glioblastoma, prostate cancer, ovarian cancer, and breast cancer by suppressing oncogenes such as EST1, ERBB2, ERBB3, and BAK1 as its targets." (PMID 28435518, 2017). "Meanwhile, inhibiting miR-125b using LNA inhibitor in the miR-125b-high MDA-MB-231 and MDA-MB-415 breast cancer cells resulted in increased E2F3, CDK2, CCNA2 and Bak1 protein expression and increased phosphorylation of Rb, which is indicative of increased G1-S progression with miR-125b inhibition." (PMID 38093346, 2023). "KDM5A promotes drug resistance of clinical drugs such as trastuzumab and erlotinib via deregulating p21 and BCL2-antagonist/killer 1 (Bak1), and facilitates the proliferation of many HER2-positive breast cancer cell lines through mediating cell cycle and apoptosis." (PMID 33596982, 2021).
Autoimmunity (12 papers, 2017 to 2025). The occurrence of an immune reaction against the organism's own cells or tissues. "AtMC2 prodomain-triggered autoimmunity is also dependent on the presence of SA, but in contrast to AtMC1 autoimmunity, it can be rescued by mutating BAK1/BKK1 or SOBIR1." (PMID 40113992, 2025). "Our genetic results thus implicated the autoimmunity in bak1 bkk1 is likely ETI-related." (PMID 28487714, 2017). "Recently, a function of the NUP107–160 complex was disclosed in autoimmunity and spontaneous cell death activated by the simultaneous loss of the receptor-like kinases (RLKs) BRI1-ASSOCIATED KINASE1 (BAK1) and its closest homolog BAK1-LIKE1 (BKK1)." (PMID 34394173, 2021). "Interestingly, overexpressing the prodomain alone of AtMC2 results in autoimmunity that requires receptor-like kinases (RLKs) BAK1/BKK1 and SOBIR1." (PMID 40113992, 2025). "Thus, in addition to their conventional role as shared co-receptors, BAK1/SERK4 constrain autoimmunity through a specific phosphor-switch on BTL2 to prevent overactivation of phytocytokine signaling." (PMID 38416059, 2024). "Additionally, CNGC (CYCLIC NUCLEOTIDE-GATED CHANNEL) calcium channels modulate Ca2+ homeostasis in the regulation of BAK1/SERK4-mediated autoimmunity." (PMID 38416059, 2024). "Indeed, disruption of the BAK1-mediated homeostatic mechanism in immune cells has been demonstrated to result in autoimmunity in mice upon BAK1 deletion." (PMID 39175752, 2024). "In addition, BAK1 associates with the BIR1 and the copain-like proteins BONZAI1 (BON1)–BON3, which are required to suppress autoimmunity." (PMID 35806456, 2022). "Additional studies revealed that BAK1 and its closest homolog, BKK1/SERK4, are not only essential to the BR signal transduction but also critical to plant autoimmunity." (PMID 41180025, 2025). "Upon detecting BAK1 depletion, BTL2 activates the Ca2+ channel CNGC20 (CYCLIC NUCLEOTIDE-GATED CHANNEL 20), in a kinase-dependent manner, to initiate plant autoimmunity." (PMID 41180025, 2025). "More recently, BAK1-mediated phosphorylation of an LRR-RK, BAK-TO-LIFE2 (BTL2), was shown to function as a phosphoswitch to prevent autoimmunity." (PMID 39345552, 2024). "In the absence of pathogens, BAK1 is constitutively sequestered by BIR2 (BAK1-INTERACTING RECEPTOR-LIKE KINASE 2) and BIR3 via physical interactions, which prevents spontaneous dimerization between BAK1 and FLS2, keeping FLS2-mediated immune responses inactive to avoid autoimmunity." (PMID 41180025, 2025).
hepatocellular carcinoma (12 papers, 2013 to 2025). A malignant tumor that arises from hepatocytes. "A previous study has established a prognostic risk model for hepatocellular carcinoma (HCC) based on five ARGs (BAK1, SPP1, BSG, PBK, and DAP3)." (PMID 40901678, 2025). "For instance, exosomal circ-0051443 has been shown to promote BAK1 expression by sponging miR-331-3p, thereby suppressing the malignant behavior of hepatocellular carcinoma cells." (PMID 40951345, 2025). "Chen and colleagues found that exosome-derived circ_0051443 repressed the malignancy of hepatocellular carcinoma (HCC) cells and HCC progression by promoting BAK1 expression." (PMID 38755265, 2024). "BAK1 is found that upregulated in NASH and ASH and is involved in the development of NASH/ASH into hepatocellular carcinoma." (PMID 35846147, 2022). "The results suggested BAK1 and CSE1L may played a synergistic role in the progression and development of hepatocellular carcinoma." (PMID 33680905, 2020).
prostate carcinoma (10 papers, 2011 to 2025). A carcinoma that arises from epithelial cells of the prostate gland.
lung carcinoma (8 papers, 2015 to 2023). "Bak-1 down-regulation has been reported in several cancers including, colorectal, gastric, and lung cancers." (PMID 37736508, 2023). "In the previous study, the downregulated genes CASP10 and CD177 and the upregulated genes BAK1, ST14, CD82, and MUC4 were detected as biomarkers for lung cancer by the joint sparse regression model." (PMID 35923697, 2022).
lymphoma (8 papers, 2015 to 2023). A malignant (clonal) proliferation of B- lymphocytes or T- lymphocytes which involves the lymph nodes, bone marrow and/or extranodal sites. "A significantly higher pro-apoptotic protein Bak1 than in the control cells was observed in Raji and U2932 lymphoma cells." (PMID 35563410, 2022). "Importantly, in our GWAS, which was also adjusted for white blood cell counts, we found association signals near genes involved in leukaemia and lymphoma development (CRK, BAK1, CDK6, MDFIC, BIK) as well as a significant enrichment of pathways related to immune cell proliferation." (PMID 33385171, 2021). "The use of calcitriol and tacalcitol increased the amount of Bak1 and miR-125b proteins, indicating that this molecule probably does not affect the level of Bak1 protein in human leukemia and lymphoma cells." (PMID 35563410, 2022). "The results showed that the level of selected miRNAs correlates with the level of proteins, especially p27, Bak1, NFκB, and CYP24A1, and miR-27b and miR-125b could be responsible for the anticancer activity of active forms of vitamin D3 in human leukemia and lymphoma." (PMID 35563410, 2022).
cervical cancer (7 papers, 2014 to 2022). A primary or metastatic malignant neoplasm involving the cervix. "miR-125b/BAK1 pathway was essential in promoting tumorigenesis and inhibiting apoptosis of cervical cancer." (PMID 36531021, 2022). "Studies demonstrated that BAK1 played a role in drug resistance and tumor proliferation in many cancers including breast, lung and cervical cancers." (PMID 34335109, 2021). "Western blot analysis revealed that OCT-3/4 was upregulated in cervical carcinoma-related tissues, indicating that its reactivation in cervical cancer cells contributes to the development and progression of cervical cancer through the miRNA-125b/BAK1 pathway." (PMID 32178477, 2020). "In the regulatory cervical cancer pathway, OCT-3/4 directly upregulates miR-125b, which downregulates its direct target BAK1; therefore, suppression of cervical cancer cell apoptosis occurs." (PMID 32178477, 2020). "Overexpression of OCT-3/4 in cervical cancer induces overexpression of miR-125b, which suppresses apoptosis and expression of BAK1 protein." (PMID 32178477, 2020). "In this study, the GSPs-treated HeLa and SiHa cells were found to express significantly less Bcl-2 protein and more Bak-1 protein than the untreated cells, suggesting that both Bcl-2 and Bak-1 play roles in GSPs-induced apoptosis in cervical cancer cells." (PMID 25187959, 2014). "Therefore, OCT-3/4 directly upregulates miR-125b, which inhibits BAK1 function, leading to the suppression of cervical cancer apoptosis." (PMID 32178477, 2020). "BAK1 protein expression has also been shown to maintain a pro-oxidant state during periods of stress by regulating cytochrome c oxidase activity and mitochondrial respiration possibly indicating a novel anti-apoptotic role of BAK1 in conferring resistance to human leukemia and cervical cancer cells." (PMID 30404157, 2018). "Therefore, GSPs induced the apoptosis of cervical cancer cells through the down-regulation of Bcl-2 and the up-regulation of Bak-1." (PMID 25187959, 2014). "Thus, the expression of Bcl-2 and Bak-1 was examined by western blotting to determine whether these two proteins are involved in the induction of cervical cancer cell apoptosis by GSPs." (PMID 25187959, 2014).
gastric cancer (7 papers, 2018 to 2025). A primary or metastatic malignant neoplasm involving the stomach. "The pro-apoptotic protein BAK1 has been identified as a prognosis marker for advanced gastric cancer after treatment." (PMID 40535818, 2025). "It was shown in gastric cancer that overexpression of BAK1 is related to induction of apoptosis." (PMID 31234549, 2019).
leukemia (6 papers, 2011 to 2024). A malignant (clonal) hematologic disorder, involving hematopoietic stem cells and characterized by the presence of primitive or atypical myeloid or lymphoid cells in the bone marrow and the blood. "Remarkably, we found that the tumor suppressor Bak1 had the most reduced activity, which suggested that Bak1 was likely to be an important target regulated by miR-125b in leukemia." (PMID 21880154, 2011).